CILP2 (cartilage intermediate layer protein 2)
Diseases named in the same sentence as CILP2 in open-access papers (continued):
Sharing a sentence is not in itself a finding about the gene and the disease.
pancreatic ductal adenocarcinoma (2 papers, 2023 to 2026). An infiltrating adenocarcinoma that arises from the epithelial cells of the pancreas. "Considering the high expression level and prognostic significance of CILP2 in pancreatic ductal adenocarcinoma (PDAC), we specifically investigated its role in PDAC." (PMID 38136386, 2023). "Additionally, we explored the immunological characteristics of CILP2 in pan-cancer and then focused specifically on pancreatic ductal adenocarcinoma (PAAD)." (PMID 38136386, 2023).
acute myeloid leukemia (1 paper, 2023). Acute myeloid leukemia (AML) is a group of neoplasms arising from precursor cells committed to the myeloid cell-line differentiation. "Skin cutaneous melanoma had the most genetic alterations in the CILP2 gene, mainly in the form of mutations, whereas there were almost no alterations in acute myeloid leukemia, cholangiocarcinoma, renal cell carcinoma, pheochromocytoma, and paraganglioma." (PMID 38136386, 2023).
adenoid cystic carcinoma (1 paper, 2023). A malignant tumor arising from the epithelial cells. "Our findings showed that high expression levels of CILP2 were associated with poor prognoses in all cancer types, especially in adenoid cystic carcinoma (ACC) and kidney renal clear cell carcinoma (KIRC)." (PMID 38136386, 2023).
age (1 paper, 2024). A temporal measurement of the time period elapsed since an identifiable point in the life cycle of an organism. "In summary, our results illustrate the advantages of silencing CILP2 on glucose metabolism, muscle fibre size and running distance in age‐related muscle atrophy." (PMID 39385717, 2024).
ankylosing spondylitis (1 paper, 2023). An autoimmune chronic inflammatory disorder characterized by inflammation in the vertebral joints of the spine and sacroiliac joints. "CILP2, located on chromosome 19p13, is thought to play an important role in the progression of ankylosing spondylitis." (PMID 38136386, 2023).
arteriosclerosis (1 paper, 2020). A vascular disorder characterized by thickening and hardening of the walls of the arteries. "Therefore, we screened THP-1 cells for arteriosclerosis-related genes after transfection with pAd-CILP2." (PMID 33204392, 2020).
central obesity (1 paper, 2019). "We further examined circulating CILP-2 levels in human and demonstrated that circulating CILP-2 levels were markedly increased in central obesity, IGT and nT2DM subjects compared with healthy controls." (PMID 30896018, 2019). "However, the subjects with central obesity (n = 163), defined by waist circumference (WC, male ≥ 94 cm and female ≥ 80 cm), had significantly higher circulating CILP-2 levels than those without central obesity." (PMID 30896018, 2019).
cholangiocarcinoma (1 paper, 2023). A carcinoma that arises from the intrahepatic biliary tree (intrahepatic cholangiocarcinoma) or from the junction, or adjacent to the junction, of the right and left hepatic ducts (hilar cholangiocarcinoma). "Notably, CILP2 showed negative correlations with MSI in stomach adenocarcinoma (STAD), colon adenocarcinoma (COAD), and cholangiocarcinoma." (PMID 38136386, 2023).
Hepatic steatosis (1 paper, 2026). Steatosis is a term used to denote lipid accumulation within hepatocytes. "Conversely, CILP2 knockout reduced high-fat diet-induced hepatic steatosis and improved glucose metabolism." (PMID 41683641, 2026).
Hypercholesterolemia (1 paper, 2022). An increased concentration of cholesterol in the blood. "We found several novel variants associated with different lipemic traits: rs3825041 in BUD13 with hypertriglyceridemia, rs7252453 in CILP2 with decreased risk to hypercholesterolemia and rs11076176 in CETP with increased risk to low high density lipoprotein cholesterol." (PMID 35669185, 2022).
Hyperglycemia (1 paper, 2019). An increased concentration of glucose in the blood. "The results of OGTT and positive correlation of HbA1c and HOMA-IR with circulating CILP-2 implicated an effect of hyperglycemia or hyperinsulinemia on CILP-2 release." (PMID 30896018, 2019). "As the increase in glucose after an oral glucose challenge is accompanied by an increase in insulin levels, it is unclear whether short-term hyperglycemia or hyperinsulinemia is responsible for the CILP-2 release." (PMID 30896018, 2019). "We speculated that elevated circulating CILP-2 levels might be due to the impairment of CILP-2 signaling in target tissues and/or the dysregulation of CILP-2, which is caused by changes in biosynthesis and release or in response to hyperglycemia, hyperinsulinemia or adipokines in IR state." (PMID 30896018, 2019). "Therefore, hyperglycemia may stimulate the secretion and release of CILP-2, as hyperglycemia promotes insulin release." (PMID 30896018, 2019).
Hyperinsulinemia (1 paper, 2019). An increased concentration of insulin in the blood. "Our results indicate that acute hyperinsulinemia failed to lead to changes of circulating CILP-2 levels." (PMID 30896018, 2019).
joint disorders (1 paper, 2012). "However it is notable that CILP2, like other high-scoring plasma protein markers such as COMP, TNXB, THBS4, SPP1, COL2A1 to name a few, are associated with connective tissue development (cartilage matrix synthesis in the case of CILP2) and bone and joint disorders." (PMID 22558154, 2012).
knee osteoarthritis (1 paper, 2020). "Serum levels of CILP-2 appear to be associated with loss of cartilage thickness in certain individuals with increased risk of developing knee osteoarthritis." (PMID 31935848, 2020).
liver cancer (1 paper, 2023). An epithelial or non-epithelial malignant neoplasm that arises from the liver. "The copy number variation analysis revealed significantly increased copy numbers of CILP2 in the endometrial, esophageal, and liver cancers, while they were significantly decreased in low-grade glioma and tenosynovial giant cell tumors." (PMID 38136386, 2023).
muscular dystrophy (1 paper, 2024). Muscular dystrophy (MD) refers to a group of more than 30 genetic diseases characterized by progressive weakness and degeneration of the skeletal muscles that control movement. "Interestingly, sh‐CILP2 also significantly decreased the expression of muscular dystrophy proteins: Atrogin‐1, MuRF‐1 and Myostatin." (PMID 39385717, 2024).
ovarian carcinoma (1 paper, 2023). A malignant neoplasm originating from the surface ovarian epithelium. "CILP2 was identified of an energy metabolism‐related gene signature in ovarian cancer prognosis." (PMID 37337170, 2023).
pancreatic adenocarcinoma (1 paper, 2023). "The results were consistent with the log-rank test, showing a significant association between CILP2 expression and prognosis in ACC, KIRC, and pancreatic adenocarcinoma (PAAD)." (PMID 38136386, 2023).
Pancreatic Cancer (1 paper, 2023). "Combining our results with previous research results, we found that CILP2 is highly expressed in pancreatic cancer tissues and increases the relative risk of pancreatic cancer, implying that CILP2 may play an important role in pancreatic cancer." (PMID 38136386, 2023). "Given the value of CILP2 in pancreatic cancer that has been revealed by previous analyses, we then investigated its role using public databases and our clinical samples." (PMID 38136386, 2023). "The expression of CILP2 has been consistently high in pancreatic cancer, as suggested by bioinformatic analyses, PCR, and IHC at multiple levels." (PMID 38136386, 2023). "Compared to the control groups, the CILP2 knockdown group exhibited lower average tumor volumes and weights while high expression levels of CILP2 resulted in larger tumor volumes and heavier tumor weights in the orthotopic pancreatic cancer model." (PMID 38136386, 2023). "In pancreatic cancer, high expression levels of CILP2 lead to decreased tumor purities and increased stromal contents, which are closely related to TAM and CAF infiltration and strongly positively correlated with the expression of immune-suppressive genes." (PMID 38136386, 2023). "Our study results will help to understand the role of CILP2 in pan-cancer tumorigenesis and progression, especially in pancreatic cancer, and they provide the basis for further immunotherapy research." (PMID 38136386, 2023). "Both the TCGA-PDAC cohort and multiple GSE datasets revealed high expression levels of CILP2 in pancreatic cancer tissues compared to normal adjacent tissues." (PMID 38136386, 2023). "Subsequently, the transwell and wound healing assays were conducted to evaluate the effect of CILP2 on the migratory and invasive properties of pancreatic cancer cells." (PMID 38136386, 2023). "Our findings will enhance the understanding of the role of cartilage intermediate layer protein 2 in pan-cancer tumorigenesis and progression, especially in pancreatic cancer." (PMID 38136386, 2023). "To investigate the function and molecular mechanism of CILP2 in pancreatic cancer cells, we generated three siRNAs to silence endogenous CILP2 expression in the CILP2-high cell line BxPC-3." (PMID 38136386, 2023). "To explore the effect of CILP2 on pancreatic cancer cell proliferation, we performed CCK-8 and colony formation assays." (PMID 38136386, 2023). "First, we generated three murine siRNAs to silence endogenous CILP2 expression in the mouse pancreatic cancer cell line Panc02, and the downregulation of CILP2 was most significant by si-CILP2-1-mouse." (PMID 38136386, 2023). "Further, the KEGG enrichment analysis indicated a significant association between CILP2 and the PI3K-AKT pathway in pancreatic cancer." (PMID 38136386, 2023). "Furthermore, the IHC analysis showed that the decreased expression of CILP2 led to decreased levels of Ki-67, N-cadherin, and vimentin, as well as increased levels of E-cadherin in the orthotopic pancreatic cancer model." (PMID 38136386, 2023). "Moreover, the subgroup analysis indicated higher expression levels of CILP2 in the more aggressive (quasi-mesenchymal/basal/squamous) subtypes of pancreatic cancer, accompanied by poorer prognoses." (PMID 38136386, 2023). "Finally, in vitro and in vivo experiments assessed the impact of CILP2 on pancreatic cancer progression." (PMID 38136386, 2023). "We demonstrated that CILP2 significantly contributes to pancreatic cancer progression." (PMID 38136386, 2023). "Additionally, the CILP2 mRNA levels were significantly increased in four pancreatic cancer cell lines, including PANC-1, BxPC-3, SW1990, and CFPAC-1, when compared to the HPDE6-C7 line." (PMID 38136386, 2023). "To investigate the role of CILP2 in pancreatic cancer progression in vivo, we developed orthotopic and liver metastasis pancreatic cancer models using stably transfected cell lines (PANC-1-Vector, PANC-1-CILP2, BxPC-3-shCtrl, and BxPC-3-shCILP2)." (PMID 38136386, 2023).
Pancreatic Cancer (continued). "The gene set variation analysis (GSVA) suggested a close relationship between CILP2 and EMT in pancreatic cancer." (PMID 38136386, 2023). "CILP2 activated the AKT pathway, and it increased proliferation, invasion, migration, and epithelial–mesenchymal transition (EMT) in pancreatic cancer." (PMID 38136386, 2023). "The results of the qRT-PCR analysis showed the significant upregulation of CILP2 in pancreatic cancer tissues compared to their corresponding adjacent non-tumor tissues." (PMID 38136386, 2023). "The knockdown of CILP2 in vitro restrained the proliferation, invasion, migration, and EMT of pancreatic cancer cells, which could be rescued by activating the AKT pathway." (PMID 38136386, 2023). "Overall, our results revealed that CILP2 might act as an oncogenic factor in regulation through the AKT pathway signaling, and it might play an oncogenic role in pancreatic cancer." (PMID 38136386, 2023). "Finally, through in vitro and in vivo experiments, we confirmed that CILP2 can regulate the proliferation, invasion, migration, and EMT of pancreatic cancer cells." (PMID 38136386, 2023).
skin cutaneous melanoma (1 paper, 2023). "The analysis of the TCGA WGS/WES data revealed pan-cancer genetic alteration changes in CILP2, with most changes being mutations, and skin cutaneous melanoma having the most genetic variation, mainly in the form of mutations." (PMID 38136386, 2023).
cancer (5 papers, 2020 to 2026). A tumor composed of atypical neoplastic, often pleomorphic cells that invade other tissues. "Due to its association with macrophage‐related subtypes, CILP2 can serve as a biomarker for prognosis across various cancers and as a potential target for immunotherapy [S35, S36]." (PMID 39385717, 2024). "We found that CILP2 is significantly upregulated in most tumors, and its abnormal methylation and copy number variations are associated with poor prognoses in various cancers." (PMID 38136386, 2023). "We investigated the genetic alteration status of the CILP2 gene in 33 types of pan-cancer, including mutations, amplifications, deep deletions, and multiple alterations." (PMID 38136386, 2023). "We evaluated the pan-cancer expression, methylation, and mutation data of CILP2 for its clinical prognostic value." (PMID 38136386, 2023). "High expression levels of CILP2 consistently accompanied the infiltration of cancer-associated fibroblasts (CAFs) and tumor-associated macrophages (TAMs)." (PMID 38136386, 2023). "Additionally, CILP2 can serve as an independent prognostic risk factor for several cancers." (PMID 38136386, 2023). "This review synthesizes evidence establishing CILP2 as a key modulator at the nexus of metabolic dysfunction, cancer, and other pathologies." (PMID 41594707, 2026). "We selected cartilage intermediate layer protein 2 (CILP2) because of high mRNA expression in PM patients in our validation cohort and its association with a poor prognosis in The Cancer Genome Atlas." (PMID 38816545, 2024). "In our study, we evaluated the pan-cancer expression level of CILP2 and found that it was significantly upregulated in most cancers." (PMID 38136386, 2023). "The survival analysis demonstrated that CILP2 was associated with the OS, PFI, DFI, and DSS in various cancers, especially with poor prognoses in ACC and KIRC." (PMID 38136386, 2023). "Our study highlights the potential carcinogenic role of CILP2 and identifies it as a prospective and promising therapeutic target for cancer and a marker of immune infiltration and poor prognosis." (PMID 38136386, 2023). "Meanwhile, in most cancers, the methylation of CILP2 has been negatively correlated with its transcriptional levels." (PMID 38136386, 2023). "In this study, we conducted an analysis of the expression level, methylation, copy number variation (CNV), prognostic role, and immune infiltration of CILP2 in pan-cancer." (PMID 38136386, 2023). "CILP2 exhibited high expression in most malignancies, with significant heterogeneity in epigenetic modifications across multiple cancer types." (PMID 38136386, 2023). "Cartilage intermediate layer protein 2 (CILP2) facilitates interactions between matrix components in cartilage and has emerged as a potential prognostic biomarker for cancer." (PMID 38136386, 2023). "Considering that MSI and TMB are currently identified as sensitive indicators for ICB in various cancers, we also analyzed the correlations between CILP2 and MSI or TMB." (PMID 38136386, 2023). "To further investigate the prognostic potential of CILP2 in cancer, we analyzed four prognostic indicators using the KM method (log-rank test) in 33 different types of cancers." (PMID 38136386, 2023). "Several studies have reported the involvement of CILP2 in cancer progression." (PMID 38816545, 2024). "Furthermore, the differential analysis of CILP2 expression revealed higher expression levels in most cancers compared to the corresponding normal tissues." (PMID 38136386, 2023). "Therefore, this study aims to explore the function and mechanism of cartilage intermediate layer protein 2 in pan-cancer." (PMID 38136386, 2023). "This study aimed to investigate the function and mechanisms of CILP2 in pan-cancer." (PMID 38136386, 2023). "This research could potentially establish cartilage intermediate layer protein 2 as a promising prognostic biomarker and immunotherapy target for cancers." (PMID 38136386, 2023).
cancer (continued). "Additionally, TGFB1/TGFBR1 exhibited positive correlations with CILP2 in nearly all cancer types." (PMID 38136386, 2023). "However, the significance of CILP2 in other cancers remains largely unexplored." (PMID 38136386, 2023). "Therefore, the abnormal methylation and CNV of CILP2 have led to poor prognoses in various cancers, indicating that the epigenetic changes in CILP2 may promote the progression of certain cancers." (PMID 38136386, 2023). "The expression levels of CILP2 showed positive correlations with the stromal score and the ESTIMATE score in most cancers, while they were negatively correlated with tumor purity and immune scores." (PMID 38136386, 2023). "The results indicated that the correlations between CILP2 and TMB varied across the different cancer types." (PMID 38136386, 2023). "Firstly, we evaluated the correlations between CILP2 and the tumor purity score, stromal score, ESTIMATE score, and immune score in pan-cancer using the ESTIMATE algorithm." (PMID 38136386, 2023). "The correlations between CILP2 and TMB differed in the various cancers, while CILP2 was negatively correlated with STAD, COAD, and CHOL." (PMID 38136386, 2023). "Second, an orthotropic model of engraftment was not employed in our analyses; therefore, evaluating the influence of CILP2 on the detachment of cancer cells from the primary tumour was not possible." (PMID 38816545, 2024). "Furthermore, our in vivo studies exhibited that CILP2 knockdown in CRC cells significantly downregulated tumour nodules, tumour weight, and ascites, indicating a decreased ability for cancer cell dissemination and growth both in vitro and in vivo." (PMID 38816545, 2024).
tumor (4 papers, 2020 to 2025). "Elevated CILP2 expression was significantly associated with the presence of PM and risk factors such as differentiation and tumour stage." (PMID 38816545, 2024). "High CILP2 mRNA levels also demonstrated an association with a poor level of differentiation and tumour stage." (PMID 38816545, 2024). "In summary, our study results indicated that CILP2 is a potential tumor prognostic biomarker and immunotherapy target." (PMID 38136386, 2023). "Further, compared with the CILP2 knockdown group and the anti-PD-L1 therapy-only group, there was significant tumor regression in the tumors in the combination therapy group." (PMID 38136386, 2023). "The CILP2 knockdown group and the anti-PD-L1 therapy-only group showed tumor regression compared with the control group, respectively." (PMID 38136386, 2023). "For the first time, we found out that CILP2 was upregulated in tumor tissues compared to normal tissues." (PMID 33099318, 2020). "Additionally, CILP2 gene expression was upregulated in the total amount of tumor samples compared with adjacent normal tissue samples in TCGA cohort (fold change = 8.6161, P < 0.001)." (PMID 33099318, 2020). "We found that 68.75% (44/64) of tumor tissues highly expressed CILP2 protein, whereas only 39.06% (25/64) of matched adjacent normal tissues highly expressed CILP2 protein." (PMID 33099318, 2020).
cardiovascular disease (2 papers, 2013 to 2021). "The aim of this study is to assess the association of two polymorphisms, the cartilageintermediate layer protein 2 (CILP2) G/T and angiotensin convertingenzyme (ACE) I/D, with blood pressure and anthropometrical andbiochemical parameters related to the development of cardiovascular disease." (PMID 24350279, 2013).